NCEH1 (neutral cholesterol ester hydrolase 1)
Description:
Hydrolyzes 2-acetyl monoalkylglycerol ether (1-O-alkyl-2-acetyl-sn-glycerol), the penultimate precursor of the pathway for de novo synthesis of platelet-activating factor. May be responsible for the hydrolysis of cholesterol esters (such as cholesteryl (9Z-octadecenoate)) in macrophages (By similarity). Also involved in organ detoxification by hydrolyzing exogenous organophosphorus compounds (By similarity). May contribute to cancer pathogenesis by promoting tumor cell migration.
Synonyms: NCEH; AADACL1; KIAA1363
Tractability: Small molecule: a high-quality ligand is known; it belongs to a druggable protein family. Antibody: UniProt places it where antibodies can reach, with high confidence; UniProt predicts a signal peptide or a membrane-spanning region; its Gene Ontology location is reachable by antibodies, with medium confidence. PROTAC: ubiquitination databases record sites on it; its protein half-life has been measured; a small molecule that binds it is known.
Target class: Enzyme; Hydrolase
Gene: Protein-coding gene on chromosome 3 (172,630,249 to 172,711,218, reverse strand). Ensembl gene ENSG00000144959.
Subcellular location: Cell membrane; Microsome
Subcellular location (Human Protein Atlas): Endoplasmic reticulum
Pathways (Reactome):
Transport of small molecules: LDL clearance
Gene Ontology:
Molecular function: serine hydrolase activity; sterol ester esterase activity; acetylalkylglycerol acetylhydrolase activity; carboxylic ester hydrolase activity; catalytic activity; hydrolase activity; phosphate ion binding
Biological process: ether lipid metabolic process; low-density lipoprotein particle clearance
Cellular component: membrane; endoplasmic reticulum membrane; plasma membrane
Genetic constraint (gnomAD): Loss-of-function variants: 7 observed, 24.87 expected, observed/expected ratio (o/e) 0.28, 90% interval 0.16 to 0.53. The upper end of that interval is the gene's LOEUF score, 0.53, which puts it in group 2 of 6, group 1 being the genes least tolerant of losing a copy. Missense variants: 381 observed, 501.2 expected, observed/expected ratio (o/e) 0.76, 90% interval 0.7 to 0.83. Synonymous variants: 192 observed, 202.33 expected, observed/expected ratio (o/e) 0.95, 90% interval 0.84 to 1.07.
Homologues: Orthologues: chimpanzee NCEH1 (99% identical), macaque NCEH1 (99% identical), guinea pig NCEH1 (93% identical), dog NCEH1 (92% identical), rabbit NCEH1 (91% identical), pig NCEH1 (88% identical), mouse Nceh1 (88% identical), rat Nceh1 (87% identical), tropical clawed frog nceh1 (60% identical), zebrafish nceh1b.1 (50% identical), zebrafish NCEH1 (50% identical), zebrafish nceh1a (50% identical), and 3 more. Paralogues in human: AADAC (43% identical), AADACL2 (38% identical), AADACL4 (30% identical), AADACL3 (28% identical), AFMID (13% identical).
Diseases named in the same sentence as NCEH1 in open-access papers:
NCEH1 is named in the same sentence as 29 diseases in open-access papers, as found by Europe PMC text mining. Sharing a sentence is not in itself a finding about the gene and the disease. The quoted sentences say what the papers report.
atherosclerosis (14 papers, 2012 to 2024). A disease characterized by the build-up of fatty material and calcium deposition in the arterial wall resulting in partial or complete occlusion of the arterial lumen. "It has been reported that the activity of NCEH1 tends to be lower in macrophage-derived foam cells and macrophages from atherosclerosis-prone C57BL/6J mice." (PMID 38664801, 2024). "Ablation of NCEH1 promotes foam cell formation and accelerates atherosclerotic lesion formation in atherosclerosis-prone mice." (PMID 38664801, 2024). "Previously, NCEH1 is more studied in macrophage and atherosclerosis, but little is known about its roles in pathogenesis, progression disparities of CRC." (PMID 35172832, 2022). "Dysregulation of NCEH1 levels is involved in the pathogenesis of multiple disorders including metabolic diseases and atherosclerosis; however, relatively little is known regarding the mechanisms regulating NCEH1." (PMID 32321446, 2020). "Genetic ablation of NCEH1 promotes CE-laden macrophages and the development of atherosclerosis in mice." (PMID 32321446, 2020). "Downregulation of NCEH1 promotes atherosclerosis by increasing the generation of macrophage foam cells." (PMID 32321446, 2020). "In contrast, the ablation of NCEH1 accelerates atherosclerosis by promoting the formation of macrophage foam cells." (PMID 32321446, 2020). "High levels of NCEH1 and LIPA have been shown to protect against atherosclerosis, and they are associated with increased cholesterol efflux." (PMID 30545366, 2018). "Neutral cholesterol ester hydrolase 1 (Nceh1), located on the cholesterol ester droplets, mediates their hydrolysis in both murine and human macrophages, and ablation of Nceh1 accelerates atherosclerosis." (PMID 30545366, 2018). "Genetic ablation of neutral CE hydrolase 1 (Nceh1) promotes foam cell formation and aggravates atherosclerosis in mice." (PMID 23072373, 2012). "Conversely, ablation of NCEH1 promotes foam cell formation and atherosclerosis in mice." (PMID 35812876, 2022). "The NCEH1 isoform accelerates atherosclerosis in ApoE−/− mice." (PMID 31653058, 2019). "Knockout of NCEH1 in ApoE‐deficient mice promoted the development of atherosclerosis without altering the serum lipid profile 95 suggesting the atheroprotective role of this enzyme." (PMID 26493158, 2016). "Thus, the impaired NCEH1 activity may result in the progression of atherosclerosis." (PMID 38664801, 2024). "NCEH1 is ubiquitously expressed in peritoneal macrophages and atherosclerotic lesions, its overexpression prevents the deposition of CE in THP-1 macrophages and attenuates the progression of atherosclerosis in mice." (PMID 38664801, 2024).
breast carcinoma (5 papers, 2017 to 2026). "Overexpression of NCEH1 has been associated with breast cancer, ovarian cancer, and other cancer types, but its relationship with GC has not been established." (PMID 38062450, 2023). "Functionally, the effects of NCEH1 silencing or overexpression on breast cancer cell growth and motility were investigated." (PMID 41592786, 2026). "Collectively, NCEH1 represents a potential novel biomarker and therapeutic target for breast cancer." (PMID 41592786, 2026). "Silencing NCEH1 suppressed breast cancer cell proliferation and migration." (PMID 41592786, 2026). "Moreover, expression of top five genes (NCEH1, RARRES3, NTN4, CFB and CYP4Z1) that are frequently co-expressed with TNFSF10 in breast cancer patients, have been detected upon transfection with miR-7641 mimic." (PMID 28827731, 2017).
ovarian carcinoma (5 papers, 2017 to 2023). A malignant neoplasm originating from the surface ovarian epithelium. "Similar to the results obtained with FLAG-tagged enzymes, an ADPL workflow coupling the family-wide FP-Bio probe and anti-NCEH1 antibodies detected active NCEH1 in SKOV3 ovarian cancer cells." (PMID 29176560, 2017). "NCEH1-dependent ADPL signal was almost entirely localized to the ovarian cancer cells relative to CD45+ cells, quantified as an ~20-fold and ~7-fold increase in raw and area-normalized NCEH1 ADPL activity, respectively." (PMID 29176560, 2017). "In platelets and ovarian carcinoma cells, HAG is metabolized to HG by an enzyme known as arylacetamide deacetylase-like 1 (AADACL1/NCEH1/KIAA1363)." (PMID 33430006, 2021). "Given the established relationship between NCEH1 activity and ovarian cancer cell aggressiveness, we applied ADPL to detect and quantify active NCEH1 in cellular co-culture and patient-derived spheroids." (PMID 29176560, 2017). "The qualitative differences between these distinct cell lines were apparent in ADPL images; the mean relative differences in NCEH1 activity between the aggressive/non-aggressive pairs from prostate and ovarian cancer cells were 18- and 35-fold, respectively." (PMID 29176560, 2017). "Image-based ADPL quantification of NCEH1 activity in dissociated individual spheroids revealed that they were not homogeneous and instead consisted of both ovarian cancer cells and CD45+ immune cells." (PMID 29176560, 2017). "To determine if these patient-derived cells were more similar to aggressive or non-aggressive ovarian cancer cell lines, we quantified NCEH1 activity in a co-culture system of CD45+ lymphocyte monocyte immune cells and aggressive SKOV3 or non-aggressive OVCAR3 cancer cells." (PMID 29176560, 2017).
prostate carcinoma (4 papers, 2022 to 2023). A carcinoma that arises from epithelial cells of the prostate gland. "It has been reported that the inactivation of NCEH1 impairs cell migration and tumor growth in ovarian and prostate cancers." (PMID 37251940, 2023). "NCEH1 inhibition has been reported to suppress prostate cancer, but it is unclear if this suppression disturbs cellular cholesterol balance." (PMID 37978383, 2023).
colorectal cancer (2 papers, 2022 to 2023). A primary or metastatic malignant neoplasm that affects the colon or rectum. "Among the mutated genes in the adenomatous tissue samples involved in our study, PCDHGB4, AHRR, KIF4, LPAR6, NBPF1, and NCEH1 were already associated with colorectal cancer formation, while ANKRD30A, ITIH1, and KIAA0556 were related to other types of cancers." (PMID 36765865, 2023). "NCEH1 and WNT10B, and ATP1A3 have been rarely reported to be associated with AD, but WNT10B has an important role in progression of colorectal cancer and hepatocellular carcinoma." (PMID 36506318, 2022).
hepatocellular carcinoma (2 papers, 2020 to 2022). A malignant tumor that arises from hepatocytes. "siRNA-mediated knockdown of RORα significantly downregulated NCEH1 expression and accumulated lipid droplets in human hepatoma cells." (PMID 32321446, 2020).
Obesity (2 papers, 2024). Accumulation of substantial excess body fat. "Thus, we provided evidence showing that NCEH1 may play a therapeutic role in vascular complications associated with obesity and diabetes." (PMID 38664801, 2024).
pancreatic cancer (2 papers, 2021 to 2023). "It has been shown that high expression of NCEH1 is associated with shorter overall survival of pancreatic cancer patients." (PMID 37958351, 2023). "Increased NCEH1 protein abundances in the tumor-adjacent tissue, rather than in the neoplastic area, is associated with shorter survival of pancreatic cancer patients." (PMID 37958351, 2023). "Regarding NCEH1, which hydrolyzes 2-acetyl monoalkylglycerol in the metabolism of ether lipids, it has been suggested as a prognostic marker for pancreatic cancer, supporting our analysis." (PMID 34078402, 2021). "Among 39 differentially expressed factors, seven up-regulated genes (CAV2, CIDEC, HILPDA, HSD17B11, NCEH1, RAB5A, and SQLE) and two down-regulation genes (BSCL2 and FITM1) were significantly associated with overall survival of pancreatic cancer patients." (PMID 34078402, 2021). "We further identified that enhanced expression of 7 genes namely CAV2, CIDEC, HILPDA, HSD17B11, NCEH1, RAB5A, and SQLE are associated with significantly shorter overall survival whereas elevated expression of BSCL2 and FITM1 correlates with longer overall survival of pancreatic cancer patients." (PMID 34078402, 2021).
arteriosclerosis (1 paper, 2020). A vascular disorder characterized by thickening and hardening of the walls of the arteries. "NCEH1 activation, which leads to the removal of cholesterol esters in lipid droplets in macrophages, may be important for the suppression of arteriosclerosis." (PMID 32321446, 2020). "The results suggested that the control of NCEH1 expression by synthetic ligands of RORα might facilitate the development of novel anti-arteriosclerosis drugs." (PMID 32321446, 2020).
diabetes (1 paper, 2024). "The present study sought to investigate whether NCEH1 improved endothelial function in diabetes, and the underlying mechanisms were explored." (PMID 38664801, 2024). "Silencing Cav-1 and upregulating ZNRF1 were sufficient to improve EDR of diabetic aortas, while overexpression of Cav-1 and downregulation of ZNRF1 abolished the effects of NCEH1 on endothelial function in diabetes." (PMID 38664801, 2024). "The vascular benefits of NCEH1 make it a promising target for the treatment of endothelial dysfunction-related complications in diabetes." (PMID 38664801, 2024). "Nonetheless, the role of NCEH1 in endothelial dysfunction associated with diabetes has not been explored." (PMID 38664801, 2024). "To investigate the potential role of NCEH1 in diabetes-induced endothelial dysfunction, we examined the activity of NCEH1 and the expression levels of NCEH1 in HG-incubated mouse aortae ex vivo, HG-induced endothelial cells in vitro, or the aortae from HFD-induced obese mice in vivo." (PMID 38664801, 2024). "NCEH1 may be a promising candidate for the prevention and treatment of vascular complications of diabetes." (PMID 38664801, 2024). "However, whether malfunction of NCEH1 is pathologically important in diabetic cardiovascular complications has yet to be fully elucidated, and whether restored NCEH1 activity effectively protected endothelial function in diabetes remains undefined." (PMID 38664801, 2024).
endothelial dysfunction (1 paper, 2024). In vascular diseases, endothelial dysfunction is a systemic pathological state of the endothelium (the inner lining of blood vessels) and can be broadly defined as an imbalance between vasodilating and vasoconstricting substances produced by (or acting on) the endothelium. "These in vivo, in vitro, and ex vivo findings collectively suggest that NCEH1 deficiency is more likely to be involved in the pathogenesis of endothelial dysfunction in obese diabetic mice." (PMID 38664801, 2024). "The current study highlighted a functional role for NCEH1 in ameliorating endothelial dysfunction in obese diabetic mice." (PMID 38664801, 2024). "Interestingly, knockdown of ZNRF1 weaken the protection of NCEH1 overexpression against endothelial dysfunction in HG-insulted mouse aortae ex vivo." (PMID 38664801, 2024). "Therefore, the aim of the present study is to clarify whether NCEH1 protects against endothelial dysfunction induced by high-fat diet (HFD), and if so, to explore the underlying molecular mechanisms involved." (PMID 38664801, 2024).
fatty liver (1 paper, 2017). "In addition, NCEH1, ABCG5, and ABCG8 are reported to be drug targets of pioglitazone and ezetimibe in the therapy of human gallbladder cholesterolosis and HFD-induced fatty liver." (PMID 29464180, 2017).
ischemia (1 paper, 2024). A hypoperfusion of the BLOOD through an organ or tissue caused by a PATHOLOGIC CONSTRICTION or obstruction of its BLOOD VESSELS, or an absence of BLOOD CIRCULATION. "NPC2 and Nceh1 expression in edge regions was up‐regulated after ischemia and significantly higher than in core regions." (PMID 39252446, 2024).
prostate tumor (1 paper, 2021). "Investigation shows that KIAA1363 is likely linked to NCEH1 pathways, as KIAA1363 inhibition results in prostate tumor suppression activity in vivo, likely through downregulation of monoalkylglycerol ether classes of neutral ether lipids." (PMID 34281263, 2021).
Sepsis (1 paper, 2021). Sepsis is defined as life-threatening organ dysfunction caused by a dysregulated host response to infection. "In septic mice, 3HB caused an elevation in Nceh1 expression in skeletal muscle, compared to both placebo-treated septic mice and healthy mice, whereas expression of the main enzyme for cholesterol esterification, Acat1, was unaffected by sepsis and 3HB." (PMID 34274000, 2021).
cancer (11 papers, 2017 to 2026). A tumor composed of atypical neoplastic, often pleomorphic cells that invade other tissues. "NCEH1 plays an initial role in converting cholesterol esters into free cholesterol, and its studies in cancer are also limited." (PMID 38062450, 2023). "NCEH1 (also known as KIAA1363) is known to lipolyze CE in macrophages and is overexpressed in various cancers." (PMID 37978383, 2023). "How NCEH1 functions in cancer growth is unclear; however, it has been shown that NCEH1 deletions upregulate levels of cholesterol esters, which play a role in signaling ER stress and apoptosis in macrophages." (PMID 34281263, 2021). "Gel-based profiling also revealed modest differences in NCEH1 activity between the two aggressive cancer cell lines, with SKOV3 cells exhibiting an ~1.6-fold increase relative to PC3 cells." (PMID 29176560, 2017). "While a strong connection between NCEH1 and lung cancer has not been established yet, its overexpression has been linked to many cancer types including ovarian and breast cancers." (PMID 34281263, 2021). "NCEH1 mRNA expression was not different between normal and cancer tissue, whereas LIPE mRNA (which encodes HSL) expression was reduced in cancer tissue." (PMID 35033184, 2022). "Of these seven, six genes—ECT2, NCEH1, TNFSF10, FNDC3B, GHSR, and SEMA6D—have either been observed at elevated expressions in tumor cells or have been documented acting as oncogenes for specific cancers in humans (genes that can transform cells into tumor cells)." (PMID 33767816, 2021). "They include CES1, HSL, KIAA1363/NCEH1, and possibly CES3, but no consensus has been reached, let alone insight into their role in cancer." (PMID 33413672, 2021).
tumor (10 papers, 2011 to 2025). "Except for ALDH3B1 and NCEH1, the other three genes have been reported to be associated with tumor progression and gemcitabine resistance in PC." (PMID 37251940, 2023). "At the single-cell level, tumor cells expressed low levels of CHST11 compared with ALDH3B1, EGFR, ERAP2, MSLN, and NCEH1." (PMID 37251940, 2023). "Furthermore, several somatic mutations in the coding sequence of NCEH1 have been identified (COSV56432875, COSV56434458, COSV56434234, COSV56433597, COSV56435557, and COSV56432580) that are associated with tumor development in the lung, liver, intestine, endometrium, and nervous system." (PMID 35736449, 2022). "Additionally, five key genes (SYT16, NCEH1, NXPE3, MB21D2, and DZIP1L) were identified, which simultaneously appeared in A→B compartment switching, TADs, and chromatin loops in tumor samples, with four of these genes located on the q arm of chromosome 3." (PMID 41049290, 2025).
infection (3 papers, 2022 to 2024). The state of being infected such as from the introduction of a foreign agent such as serum, vaccine, antigenic substance or organism. "In sharp contrast, endothelial-specific overexpression of NCEH1 by adeno-associated virus (AAV) infection improved EDR in aortic rings from mice under HG conditions although EDR was similar between control and NCEH1 overexpression mice." (PMID 38664801, 2024).
cardiovascular diseases (1 paper, 2024). "This would shed light to the life span of NCEH1 mode of activity in vivo, as possible therapeutic targets for cardiovascular diseases." (PMID 38664801, 2024).
NCEH1 also shares sentences with these, for which no sentence is quoted: glioma (2 papers); adenoma (1); breast tumours (1); cervical cancer (1); gallbladder cholesterolosis (1); liver fibrosis (1); metabolic disease (1); neuropathy (1); vitamin A deficiency (1); Wilms tumor (1).